KRAS (KRas proto-oncogene, GTPase)
Diseases named in the same sentence as KRAS in open-access papers (continued):
Sharing a sentence is not in itself a finding about the gene and the disease.
cancer (continued). "Although not statistically significant, these findings suggest potential sex-based differences in KRAS mutation prevalence under constrained health literacy conditions and highlight the utility of AI-HOPE-PM for uncovering multidimensional disparities in cancer genomics and treatment." (PMID 41342165, 2025). "While early-stage cancer detection using liquid biopsy remains challenging, it can complement tissue testing by identifying actionable mutations like KRAS and EGFR even in non-metastatic and locally advanced stages, guiding personalized treatment in a timely manner." (PMID 40282516, 2025). "The newly-emerged CRISPR prime editing technology holds tremendous promise as a highly precise editing tool for altering KRAS mutations while preserving WT KRAS functions within the targeted cancer cells without the need for double-strand breaks like the conventional CRISPR-Cas9 system." (PMID 39820726, 2025). "This apparent 100-fold difference in the concentration required to inhibit KRAS and elicit an efficacious anti-cancer response motivated us to explore the possibility that activation of NRF2 may form an important auxiliary component of the clinical effect of G12Ci drugs in patients." (PMID 40890297, 2025). "By modifying these pan-KRAS siRNAs with a high proportion of 2′-O-methyl modifications (Hi2OMe), which confers improvements in metabolic stability within the endosomal compartment, we found that the KRAS siRNAs (Kseq2 and Kseq3) retained potent RNAi activity in several cancer cell lines." (PMID 40762837, 2025). "However, the use of ERK MAPK inhibitors for the treatment of PDAC and other KRAS-mutant cancers has been challenging owing to on-target toxicity, acquired resistance, and loss of ERK-dependent negative feedback loops, which ultimately cause reactivation of ERK signaling through RTKs and WT KRAS." (PMID 40829181, 2025). "Therefore, improvements in the current understanding of KRAS signaling in cancer cells may aid in developing novel therapeutic strategies for KRAS‐mutant cancer." (PMID 40569151, 2025). "Furthermore, DA-Raf expression is silenced in KRAS-mutant human cancer cell lines." (PMID 41120211, 2025). "Despite recent advances in KRAS-targeted therapies, treatment resistance and limited therapeutic options necessitate advanced preclinical models, such as organoids, to identify personalized cancer therapies by screening novel therapeutic strategies and synergistic drug combinations." (PMID 40275403, 2025). "However, being in the early stages, current research efforts investigating these immune-based treatment approaches in KRAS-mutant tumors are expected to provide extremely useful knowledge, influencing the development of personalized cancer treatments in the future." (PMID 40075634, 2025). "Oncogenic mutations in KRAS commonly occur at codons 12, 13, or 61 across various cancers, leading to constitutive activation independent of EGFR signaling and promoting oncogenic signaling through pathways such as the mitogen-activated protein kinase (MAPK) cascade." (PMID 40949096, 2025). "Therefore, despite the use of potentially effective KRAS G12Cinhibitors, cancer cells may maintain their viability." (PMID 40597785, 2025). "Activation of the KRAS pathway by Pin1 is particularly important for the development of pancreatic ductal adenocarcinoma (PDAC), one of the most aggressive and lethal tumors, which is projected to become the second leading cause of cancer-related deaths by 2030 in the United States." (PMID 41322199, 2025).
cancer (continued). "Consequently, for tumors with KRAS or BRAF mutations (such as colon and pancreatic cancers) that exhibit high GLUT1 expression and low SVCTs expression, extracellular DHA treatment competitively inhibits glucose uptake by cancer cells." (PMID 40950984, 2025). "For instance, a finding using CRISPR-based engineering with higher fidelity discovered that KRAS (G12C) mutants primarily react to covalent-specific G12C inhibitors once EGFR is suppressed, whereas KRAS (G12D) mutants remain susceptible to EGFR inhibition in pancreatic human cancer model." (PMID 40075634, 2025). "The oncogenic KRAS G13D mutation in MDA-MB-231 may explain the suppression of the IFN-I response and the activation of NF-κB signaling and IL-6 expression, which have been already reported for KRAS-mutated cancers." (PMID 40691137, 2025). "This vaccine may in the future be useful against many other KRAS-driven cancer types." (PMID 40437549, 2025). "According to several studies, the KRAS mutation accounted for approximately 50%, the PTEN mutation for 35%, and the CTNNB1 mutation for 12%.5,14,15 In some patients, cancer genomic profiling tests may reveal mutations, being useful for selecting a treatment method." (PMID 39896229, 2025). "Targeting KRAS-driven cancers may be achieved by interfering with the activation of KRAS by SOS1." (PMID 40244134, 2025). "For example, in Ontario, the Comprehensive Cancer Biomarker Testing Program offers biomarker testing, but the testing is limited to specific testing sites and is only available for certain cancer types and testing indications (e.g., KRAS testing for patients with advanced CRC)." (PMID 40558235, 2025). "Therefore, it is imperative to develop alternative options for treating KRAS-mutant cancers." (PMID 40091835, 2025). "However, the beyond mechanisms of KRAS-modulated cancer metabolisms remain incompletely understood." (PMID 39806421, 2025). "Collectively, our data support the hypothesis that KRAS mutations enhance the capacity of the REGγ-proteasome by increasing REGγ expression, highlighting the potential of ubiquitin-independent proteasome inhibition as a therapeutic approach for pan-KRAS–mutant cancers." (PMID 40091835, 2025). "In addition to cell proliferation, we subsequently investigated whether expression of the anti‐KRAS DARPin 784_F5 also affects anchorage‐independent growth of cancer cells." (PMID 40517320, 2025). "Consequently, the cancer-promoting effect of NAT10 in KRAS wild-type cells is relatively weak." (PMID 39905540, 2025). "However, recent advances have led to the development of therapies for KRAS-driven cancers." (PMID 39806421, 2025). "Therefore, other treatment strategies, including epigenetic modifiers, may be useful for treating KRAS-mutant cancers." (PMID 38992694, 2024).
cancer (continued). "Although sotorasib was considered KRAS G12C specific and is FDA-approved for KRAS G12C mediated cancers only, studies have indicated it may be suitable for other NRAS or HRAS G12C-mutated cancer, delivering potential to revolutionise the way in which the drug can be used." (PMID 39372214, 2024). "However, the mechanism through which cancer cells re-express KRAS is not fully understood." (PMID 38225225, 2024). "However, the cytotoxicity of BRAF and CRAF siRNAs is enhanced when ATG7 is knocked down, suggesting that KRAS-driven metabolic alterations in cancer cells make them particularly dependent on the autophagy pathway as a survival mechanism when the RAF/MAPK pathway is acutely inhibited." (PMID 39272847, 2024). "Moreover, sensitivity did not seem to correlate with KRAS mutation status or KRAS dependency, as defined by a previous report and data from the Cancer Cell Line Encyclopedia (CCLE)." (PMID 38992694, 2024). "Consequently, this presents a broad therapeutic option for patients with KRAS-driven cancers." (PMID 39001451, 2024). "Similarly, other researchers used CRISPR-Cas9 to target the KRAS gene in human cancer cells." (PMID 38195537, 2024). "Hence, it is vital to obtain more insights into how the oncogenic KRas signalling leads to cancers." (PMID 37833074, 2024). "Regarding UVA, KRAS status was associated with cancer recurrence (0.0392), but not regarding MVA." (PMID 39335120, 2024). "However, KRAS-mutant cancers are complex because of differences in KRAS dependency." (PMID 38992694, 2024). "Identified therapeutic targets span a wide spectrum,ranging from those with obvious connections to those that might bemore obscurely related to cancer immunotherapy nonetheless being increasinglyinvestigated in the context of cancer immunotherapy (KRAS, kinaseinhibitors etc.)." (PMID 38787632, 2024). "The relevance of miRNAs in cancer is exemplified by the fact that the second ever identified miRNA, namely lethal-7 (let-7), was found to be a negative regulator of the Ras family of guanosine triphosphatases (GTPases), oncogenic in many tumor types including LC (e.g. KRAS)." (PMID 38972997, 2024). "Our results, which combined diverse cell lines with tumoroids and in vivo models of KRAS-mutant cancers, suggest that Mediator kinase inhibitors may be broadly effective in blocking short- and long-term transcriptional changes required for the emergence of drug resistant cell populations." (PMID 38822082, 2024). "Therefore, we expected that SUMOylation inhibition might be beneficial for treating KRAS-mutant cancers." (PMID 38992694, 2024). "As mentioned in the Introduction, “total TF” was recently implicated in the development of resistance to KRAS-G12C inhibitors; as such, asTF-targeting via hRabMab1 may hold future promise in tackling this phenomenon in PDAC and other cancers driven by mutant KRAS." (PMID 38473827, 2024). "Studies highlight the impact of KRAS mutations on metabolic reprogramming, offering insights that could lead to novel therapeutic strategies targeting metabolic vulnerabilities in RAS-driven cancers." (PMID 39001451, 2024). "Moreover, designing prospective clinical SMARCA4-mutated or SMARCA4/KRAS-co-mutated NSCLC trials to evaluate targeted therapies and immunotherapy may lead to a better understanding of how to improve cancer patients’ outcomes and survival rates." (PMID 39063938, 2024).
cancer (continued). "The human KRAS protein is both friend and foe; the non-mutated form is indispensable in diverse physiological processes, whereas the mutated versions directly underlie multistep processes of tumorigenesis and progression in ~30% of all cancers." (PMID 38216551, 2024). "Therefore, we propose a comprehensive review aimed at exploring the research hotspots and directions in the field of Kirsten rat sarcoma viral oncogene homolog (KRAS)-mutant cancers over the past decade, providing valuable insights for cancer treatment strategies." (PMID 38706597, 2024). "Therefore, the diminished gene expression in KRAS mutant CRC cells indicates that the process of autophagy might have dual consequences depending on the cancer cell type and, thus, plays a crucial role in overall cell survival." (PMID 39057088, 2024). "In addition, research on cancer vaccines in the setting of KRAS mutant cancers is ongoing as well." (PMID 38731892, 2024). "Despite the activation of the p44/42 MAPK pathway by mutant KRAS, compensatory feedback activation has been reported to be associated with failure of MEK inhibitors as a monotherapy in clinical trials for the treatment of PDAC and other cancers harboring KRAS mutation." (PMID 38409090, 2024). "In addition, KRAS mutation is positively correlated with the TMEM16A protein, a calcium-activated chloride channel associated with tumorigenesis and progression in various cancers." (PMID 38481800, 2024). "Finally, we demonstrate that uptake of the mAb into cancer cells results in inhibition of KRAS signalling, in vitro, suggesting that an antibody-based approach to target the fully open state of G13D is a compelling and exciting possibility for future therapeutics." (PMID 39179604, 2024). "However, mutations caused by NRAS, KRAS, BRAF, PI3KCA, and Akt activation in cancers may confer the cancer cells’ therapeutic resistance to cetuximab and render it a less effective anti-cancer agent." (PMID 37507626, 2024). "We assessed whether SUMOylation inhibition was effective in KRAS-mutant cancer cells." (PMID 38992694, 2024). "While this development holds promise for cancers bearing this specific KRAS alteration, it is important to note that the G12C mutation is not the only common mutation, and it does not provide advantages for patients with amplified or other KRAS variants." (PMID 39457457, 2024). "Alternative therapeutic approaches include inhibiting the interaction of farnesylated KRAS with cGMP phosphodiesterase delta (PDEδ) using small molecule inhibitors including deltarasin; however, this approach is not selective for cancer cells and causes systemic toxicities." (PMID 38473386, 2024). "In particular, the KRAS rs8720 and NRAS rs14804 SNPs play an important role in these patients, especially where certain genotypes are associated with a higher risk of disease progression and more aggressive clinical features, including lymph node spread and advanced cancer stages." (PMID 39867023, 2024). "We next addressed whether driver mutations existed at other genomic loci in EGFR and in KRAS using an independent ultradeep sequencing platform in a separate group of patients with and without cancer (n = 81)." (PMID 37020004, 2023). "Whilst our data mean that we do not now think that rare codons explain why KRAS is more often mutated in cancer, the rare codon experiments and work by others have conclusively demonstrated that Ras dosage has a significant influence on Ras oncogenic potential." (PMID 36864243, 2023).
cancer (continued). "However, this relationship may instead offer insight into a metabolic mechanism of resistance in KRAS-mutant cancers that is promoting survival independently of KRAS." (PMID 37141389, 2023). "None of the molecular alteration examined (oncogene KRAS mutation, let-7a gene methylation, let-7a expression downregulation) was able to distinguish between cancer- bearing and cancer-free mice even though each one of these events plays a pivotal role in carcinogenesis." (PMID 37511536, 2023). "Thus, as we have discussed recently, improving circulatory problems might be a prerequisite for effective cancer therapeutics in many cases, including those targeting KRAS and G4." (PMID 37158894, 2023). "Furthermore, understanding the TME and the role of immune cells in KRAS-mutant cancers is crucial." (PMID 37662925, 2023). "To this end, we compared compound-proteome interaction signatures to compounds that are known to be effective against particular mutants of KRAS, which were then used to generate novel predictions of compounds and synergies that may be effective against KRAS-mutant driven cancers and validated." (PMID 36674513, 2023). "However, inhibition of SPH2 could enhance the sensitivity of KRAS-amplified cancer model to MEK inhibition." (PMID 37808191, 2023). "Previous studies have demonstrated that KRAS-SHP2-MAP kinase pathway-targeted agents induce expression of multiple chemokines in KRAS-mutant lung cancer cell lines and may provide a mechanism by which oncogene-targeted drugs induce cross-talk between cancer cells and the tumor microenvironment." (PMID 36845684, 2023). "Interestingly, KRAS-mutant cancers were more vulnerable to ARL-17477 than KRAS-wild-type cancers." (PMID 37402770, 2023). "Hence, an in-depth understanding of the complex interactions between KRAS mutations and PDAC may facilitate the development of therapeutic strategies for reversing the progression of malignant tumors." (PMID 38268915, 2023). "Therefore, distinctions in KRAS sequence variation rates between YO and LO cancers may carry complex implications for prognosis, treatment strategies, and perhaps even screening recommendations." (PMID 38032636, 2023). "However, G6PD-mediated carcinogenic effects are dispensable in KRAS-mutant cancer cells." (PMID 36755301, 2023). "Therefore, a comprehensive understanding of the interactions between KRAS mutations and PDAC may expediate the development of therapeutic strategies for reversing the progression of malignant tumors." (PMID 38268915, 2023). "To further explore the role of ncRNA and miRNA in KRAS-mutated CRC, we analyzed 47,841 genes using TAC software to determine statistically significant alteration in gene expression that is associated with apoptosis, cell proliferation, and cancer regulation as a consequence of reovirus treatment." (PMID 37873786, 2023). "Additionally, it also has been reported that YAP may be associated with resistance to cancer target therapy in cancer cells harboring NRAS, KRAS, or BRAF mutations 22-25." (PMID 36619222, 2023). "This can be used to target cancers with overexpression of oncogenes, for example, mitotic arrest deficiency 2 (MAD2) and protein-coding phosphatase 2 (PP2A), cyclin-dependent kinase regulatory subunit 1B (CKS1B) and Polo-like kinase 1 (PLK1), KRAS and CDKN1A (p21)." (PMID 37896193, 2023).